BDNF (brain derived neurotrophic factor)
Diseases named in the same sentence as BDNF in open-access papers (continued):
Sharing a sentence is not in itself a finding about the gene and the disease.
cancer (continued). "At the same time, high concentrations of BDNF are associated with tumor growth, metastasis, and poor survival in cancer patients." (PMID 38612708, 2024). "It has been previously shown that brain-derived neurotrophic factor is linked with various types of cancer." (PMID 38775506, 2024). "This study examined the relationships between a single-nucleotide polymorphism (SNP) of brain-derived neurotrophic factor (BDNF) rs6265 and psychoneurological (PN) symptoms in female cancer survivors." (PMID 37462904, 2024). "Brain-derived neurotrophic factor (BDNF) is a class of neurotrophins associated with decreased sensitivity to cisplatin, etoposide, and vinblastine in numerous cancers." (PMID 36832001, 2023). "An overexpression of TrkB and BDNF is linked to poor prognosis in certain types of cancer, such as NSCLC." (PMID 36794673, 2023). "In contrast, a downregulation of BDNF levels over time is associated with worsened cognitive outcomes in anthracycline-receiving cancer participants." (PMID 37770565, 2023). "Clinical studies have suggested that brain-derived neurotrophic factor (BDNF) is linked with a positive impact on cognition in patients with cancer." (PMID 36720792, 2023). "TrkB is essential to BDNF function because TrkB deficiency in an ADK model reduces cancer’s ability to generate metastasis." (PMID 36289793, 2022). "In ultramarathon athletes, miRNA expression change share pathways associated with cancer and inflammation, as well as BDNF signalling." (PMID 36361944, 2022). "After treatment with cisplatin, a higher miR-16 expression associated with greater BDNF levels significantly reduces cancer cell differentiation and growth." (PMID 35916975, 2022). "BDNF has been implicated in angiogenesis through the regulation of the VEGF‐HIFs axis in different cancers." (PMID 35586989, 2022). "At the same time, research results suggest that IL-6 levels are negatively associated with BDNF levels in cancer patients with depression." (PMID 34841285, 2021). "While the mechanism of chemotherapy or cancer-induced inflammation is better defined, the exact cause of chemotherapy related BDNF decline is still unclear." (PMID 33985854, 2021). "Overexpression of BDNF has been associated with increased invasiveness in several cancers and implicated in the pathogenesis of PNI in pancreatic cancer." (PMID 34885121, 2021). "Many scientific articles underlined BDNF as a prognostic biomarker in predicting CIPN in cancer patients." (PMID 33920318, 2021). "Although serum levels of BDNF have been considered to have diagnostic value in several human cancers, there is a deficiency in its application for the diagnosis of CRC." (PMID 33628340, 2021). "In the present study, we attempted to profile the pan-cancer expression of BDNF at cell and mRNA level and the association between its abnormal expression and patient outcomes." (PMID 34777634, 2021). "Recent studies, including ours, have demonstrated that BDNF and TrkB play a crucial role in tumorigenesis and cancer metastasis, and are associated with poor survival in patients with various cancer types." (PMID 32731498, 2020). "BDNF-TrkB signaling pathway mediates metastatic effect through modulation of cancer-associated fibroblasts (CAFs) as demonstrated in mouse model co-injected with OSC19-Luc transfected cell line and CAFs." (PMID 29334991, 2018). "Given the possible implication of BDNF in cognition, it is worthwhile exploring the possible association of peripheral BDNF levels and cognitive function in the chemotherapy-receiving cancer population." (PMID 29258453, 2017). "Thomaz A suggested that BDNF is associated with increased proliferative capabilities, invasiveness, and chemoresistance in several types of cancer." (PMID 27852063, 2016). "During exercise, myokines such as brain-derived neurotrophic factor (BDNF) inhibit the release of myostatin, thus helping to slow the rate of muscle loss in advanced cancer patients." (PMID 29152403, 2016).
cancer (continued). "Loss of miR-204 has recently been shown to promote cancer cell migration via increased expression of brain derived neurotrophic factor or its receptor, TrkB." (PMID 24025188, 2013). "Brain derived neurotrophic factor (BDNF) is a small-molecule protein from the neurotrophin family of growth factors that is associated with the disease status and outcomes of cancers." (PMID 23874483, 2013). "Overexpression of BDNF/TrkB was also found to associate with increased metastatic potential of several malignant tumors." (PMID 24403258, 2013). "Similar to the current study, higher BDNF expression was significantly associated with nodal positivity, local recurrence, death from cancer, and poor overall prognosis." (PMID 23531103, 2013). "The brain-derived neurotrophic factor (BDNF) is a small molecule in the neurotrophin family of growth factors that is associated with the disease status and outcome of cancers." (PMID 23892595, 2013). "In these cancers, increased expression of TrkB and/or BDNF is associated with poor clinical outcomes." (PMID 22911740, 2012). "Our results show that loss of miR-204 promotes BDNF (or EGF)-induced cancer cell migration and invasion by activating AKT/mTOR pathway leading to Rac1 translocation and actin reorganization." (PMID 23285024, 2012). "Since TrkB expression is associated to several cancers; the goal of this study was to define the conditions of endogenous secretion of BDNF and expression of neurotrophin receptors in CRC." (PMID 21966426, 2011). "While NCs lack a cancer diagnosis, there might be other unknown health conditions and/or lifestyle factors associated with circulating cytokine and BDNF levels that may have contributed to these observed changes." (PMID 40597835, 2025). "Our current findings expand on these results, proposing a new hypothesis that the influence of the BDNF polymorphism on cancer-related fatigue severity depends on sex." (PMID 37462904, 2024). "This suggests that BDNF rs6265 polymorphism may have a protective advantage against cancer-related fatigue in male cancer patients." (PMID 37462904, 2024). "The association between cancer and reduced serum BDNF levels may be mediated by confounding factors." (PMID 38928583, 2024). "The cancer-related fatigue score was associated with the BDNF rs6265 Met/Met genotype (slope = 6.00, p = 0.048), years since cancer diagnosis (slope = -0.19, p = 0.03), those with a master’s/PhD (slope = -2.73, p = 0.01), and those who are unemployed (slope = 4.84, p = 0.01)." (PMID 37462904, 2024). "Additionally, aberrant BDNF levels have been implicated in broader health issues, potentially including cancer, cardiovascular diseases, metabolic disorders, age-related diseases, immune system disorders, etc.." (PMID 38988887, 2024). "Given the role of BDNF in neuronal development, differentiation, and plasticity, it is plausible that adverse symptoms, especially those associated with cancer and its treatment, may result from mutations to this neurotrophin." (PMID 37462904, 2024). "However, on the other hand, BDNF’s binding to the tyrosine kinase receptor TrkB is highly expressed in many malignant tumors and is associated with poor prognosis." (PMID 38411074, 2024). "Factors associated with lower BDNF levels include a diagnosis of cancer (β = − 10.3, 95% CI − 13.7 to − 6.9, p < 0.001), female sex (β = − 2.8, 95% CI − 5.4 to − 0.1, p = 0.039), and time (in days) from baseline (β = − 0.018, 95% CI − 0.025 to − 0.010, p < 0.001)." (PMID 37770565, 2023). "Carriers of the rs6265 Met allele were observed with abnormal activity-dependent BDNF secretion which may contribute to the differential risks of CRCI prior to cancer treatment initiation." (PMID 37770565, 2023).
cancer (continued). "We have observed that cancer participants who have homozygous Met genotype of the BDNF Val66Met polymorphism performed better in the executive function domain, with fewer participants reporting a decrease in BDNF levels at 6-months from baseline if they were carriers of the Met alleles." (PMID 37770565, 2023). "In several types of cancer, increased expression of BDNF has been implicated in the metastasis." (PMID 37460933, 2023). "Since its discovery, BDNF has been implicated in survival and differentiation of various neuronal populations, modulation of synaptic activity, expression of genes required for long-term effects, and even on the survival of cancer cells through anoikis." (PMID 37238659, 2023). "We hypothesize that BDNF is associated with cognitive function and is thus a predictive and monitoring biomarker of cognition among cancer patients." (PMID 37770565, 2023). "Recent clinical studies have suggested a common single-nucleotide polymorphism of brain-derived neurotrophic factor (BDNF), Val66Met (rs6265), may be related to the severity of fatigue following cancer treatment." (PMID 35558437, 2022). "However, high levels of BDNF are thought to be associated with more aggressive malignant behavior and a poor prognosis in human cancer." (PMID 33628340, 2021). "Moreover, we explored the association between Th2 cells and BDNF expression in multiple cancer types." (PMID 34777634, 2021). "In the present study, we found that aberrant expression of BDNF was significantly associated with patient prognosis in several types of cancer, with a particularly remarkable association of high BDNF expression with poor prognosis and aggressive clinicopathological characteristics of PAAD patients." (PMID 34777634, 2021). "Thus, the use of hNGF1–14 peptides to sustain BDNF and ChAT levels is of interest for several human diseases associated to cholinergic disturbances, like AD, PD, DS and cancer." (PMID 32024191, 2020). "Since the Val66Met genotype is associated with reduced activity-dependent secretion of both pro- and mature BDNF, it is conceivable that carrying the Met allele affords protection against cancer-related fatigue by reducing the proapoptotic effects of proBDNF48." (PMID 32848137, 2020). "The results suggest that the BDNF Val66Met polymorphism confers protective advantage against cancer-related fatigue; whereas having the Val/Val genotype may be a genetic risk factor." (PMID 32848137, 2020). "Data from the Danish National Register of Patients indicated a significantly greater all-cause mortality risk in elderly women with low plasma BDNF levels, independently of education, CNS disease, cardiovascular disease, cancer, respiratory disease and low-grade inflammation." (PMID 20404913, 2010). "Considering observed associations of these measures with cancer status and treatment trajectory, along with circulating BDNF levels and cognitive function measures, newer epigenetic clocks reflecting health status may have utility as biomarkers in survivorship care." (PMID 41403898, 2025). "Additionally, since cancer-related fatigue is a reported predictor of many co-occurring PN symptoms, understanding the relationship of BDNF rs6265 polymorphism with cancer-related fatigue will elucidate the potential genomic mechanisms underpinning the co-occurrence of cancer-related PN symptoms." (PMID 37462904, 2024). "In addition to serving as a diagnostic and prognostic biomarker, BDNF may affect cancer treatment through various mechanisms." (PMID 39648800, 2024). "With the Met allele being responsible for leading to the reduced release of BDNF, lowered BDNF levels in the brain and subsequently brain dysfunction and memory loss, it is possible that these psychological symptoms experienced by cancer patients could be contributed by neuronal dysfunction." (PMID 35528795, 2022).
cancer (continued). "In a longitudinal study, 51 newly diagnosed Adolescent and Young adult cancer patients and 8 age-matched healthy controls provided blood samples for DNAm and BDNF measurements with concurrent clinical assessments (#NCT03476070)." (PMID 41403898, 2025). "In a subgroup analysis of the CNS and cancer, qigong and yoga showed increased BDNF and IL-6, respectively." (PMID 40281902, 2025). "We evaluated the relationship of epigenetic ageing with cancer status, circulating BDNF levels, and measured cognitive function." (PMID 41403898, 2025). "In the subgroup analysis of CNS, qigong and yoga increased the levels of BDNF but decreased IL-6; however, in the subgroup analysis of cancer, the levels of IL-6 were increased." (PMID 40281902, 2025). "This study examined the expression and localization of BDNF and NE neuron-specific proteins in the LC of mice with cancer-induced bone pain (CIBP)." (PMID 40811566, 2025). "BDNF primarily exerts its effects through the TrkB receptor, which is expressed on cancer cells, nerves, and stromal components." (PMID 41009819, 2025). "Overall, these findings underscore the complex role of pro-inflammatory and anti-inflammatory cytokines, as well as BDNF, as potential biomarkers in cancer and chemotherapy outcomes." (PMID 41155372, 2025). "Activation of the BDNF-TrkB pathway enhances cancer cell proliferation, survival, and invasion by stimulating downstream signaling cascades, including PI3K/AKT, MAPK, and STAT3 pathways." (PMID 41009819, 2025). "Opioid treatments for non‐cancer pain have also been shown to reduce peripheral BDNF levels, with levels increasing during opioid withdrawal—a phenomenon suggestive of central pain re‐sensitisation." (PMID 40222813, 2025). "Elevated BDNF levels have been observed in aggressive cancers, such as glioblastoma, colorectal cancer, and non-small cell lung cancer (NSCLC)." (PMID 41009819, 2025). "We are the first study to observe accelerated ageing among AYA cancer patients receiving treatment over time, which influenced circulating BDNF levels and cognitive function measures." (PMID 41403898, 2025). "Recent research, including our own, has identified BDNF as a crucial element in the development and progression of various types of pain, such as neuropathic, inflammatory, cancer-related, postsurgical, chronic pain, and other forms of physical discomfort." (PMID 40064496, 2025). "TYP contributed to substantial improvements in plasma levels of BDNF and ghrelin in this heterogeneous cohort of cancer survivors." (PMID 41128015, 2025). "The expression levels of BDNF and NGF genes were elevated in the cancer group receiving chemotherapy combined with supplements and chemotherapy combined with aerobic exercise, with BDNF and NGF genes exhibiting a significant increase relative to other groups." (PMID 40989799, 2025). "Future research should focus on validating biomarker panels (cytokines + BDNF) in longitudinal human studies, optimizing both diagnosis and personalized interventions to protect cognitive health in cancer survivors." (PMID 41155372, 2025). "Beyond effects on cancer cells, TrkB is expressed by human dendritic cells, and BDNF alters their maturation, indicating plausible interfaces with antigen presentation and T-cell priming." (PMID 41567220, 2025). "A statistically significant increase in plasma levels of BDNF and ghrelin was observed in cancer survivors following a 16-week yoga intervention, indicating potential therapeutic benefits of yoga in this population." (PMID 41128015, 2025). "Previous human studies revealed a marked reduction in plasma brain-derived neurotrophic factor (BDNF) post-chronic chemotherapy, linking this decline to a substantial cognitive dysfunction among cancer survivors." (PMID 39696694, 2024). "Collectively, these studies support an overall strategy for enhancing BDNF in vivo to improve cognitive function following cytotoxic cancer therapies." (PMID 39696694, 2024).
cancer (continued). "In conclusion, I3C exhibits great potential as a neuroprotective drug and BDNF modulator, with applications ranging from cancer prevention and treatment to neuroprotection." (PMID 39061415, 2024). "Clinical investigations have revealed a noteworthy correlation between the levels of brain-derived neurotrophic factor (BDNF) and cognitive outcomes in cancer patients exposed to systemic chemotherapy." (PMID 39696694, 2024). "Another study exploring the cancer-SCs crosstalk demonstrated that BDNF/TrkB axis plays a crucial role in the PNI progression via the EMT induction in salivary ACC." (PMID 39906323, 2024). "As such, this review summarizes and analyzes the impact of BDNF on neurogenic diseases, cancer, and cardiovascular diseases." (PMID 39648800, 2024). "Overexpression of hsa-miR-134-5p in cancer cells exerts regulatory effects on BDNF and SEMA4C, thereby promoting the proliferation and invasion of SW1990 cells while inhibiting apoptosis." (PMID 38579169, 2024). "More and more studies have shown that BDNF can potentially increase the growth, survival, proliferation, and migration of cancer cells, affecting cancer development." (PMID 39648800, 2024). "Participants with the Met/Met BDNF genotype reported significantly worse cancer-related fatigue and neuropathic pain." (PMID 38254671, 2024). "Recently, the BDNF/TrkB pathway was also shown to activate the epidermal growth factor receptor, a widely upregulated growth factor receptor in many cancers." (PMID 39648800, 2024). "BDNF promotes cancer progression, reduces chemotherapy responsiveness, and enhances angiogenesis by increasing cancer cell survival, proliferation, migration, and invasion." (PMID 39648800, 2024). "Virtually all of these studies affirm the potential of BDNF‐related indicators in cancer diagnosis and prognosis." (PMID 39648800, 2024). "Such neuron-cancer synapses induce the release of neuroligin-3, dopamine and brain-derived neurotrophic factor (BDNF)." (PMID 38672638, 2024). "Activation of the BDNF-TrkB signaling pathway can exert oncogenic effects, including promoting cancer cell survival and growth and decreasing chemotherapeutic sensitivity." (PMID 38348396, 2024). "Based on these findings, the potential application of BDNF as a biomarker for the diagnosis, prognosis, and treatment of cancer and cardiovascular diseases has been validated." (PMID 39648800, 2024). "The limited number of studies evaluating BDNF expression in serum of cancer patients have produced diverse results." (PMID 39143551, 2024). "It has been demonstrated that the synthesis of chemicals like brain-derived neurotrophic factor (BDNF) by neurons can promote cancer growth by boosting angiogenesis." (PMID 38523646, 2024). "The authors assume that the BDNF level is essential in establishing the program of cellular pathophysiology, being a critical factor in regulating homeostasis and the development of cancer or neurodegenerative disorders." (PMID 38612708, 2024). "Several studies have explored the potential of BDNF, its receptors, and signaling pathways as biomarkers for various cancers." (PMID 39648800, 2024). "In female cancer survivors carrying the BDNF Met/Met genotype, lower BDNF serum levels result in more severe fatigue." (PMID 37462904, 2024). "Further studies should be conducted to evaluate the clinical significance of raising BDNF plasma levels in cancer patients to a comparable level as a non-cancer individual for cognitive protection." (PMID 37770565, 2023). "The synthesis of brain-derived neurotrophic factor by CAFs was driven by lactate in cancer cells in an NF-κB-dependent way, which in turn activated TrkB/Nrf2 signalling in cancer cells to lessen their susceptibility to anlotinib." (PMID 37569598, 2023). "This study presents the results of longitudinal cognitive assessments as well as plasma BDNF levels during cancer treatment at 3- and 6-months post-baseline." (PMID 37770565, 2023).